CHAC1 (ChaC glutathione specific gamma-glutamylcyclotransferase 1)
Diseases named in the same sentence as CHAC1 in open-access papers (continued):
Sharing a sentence is not in itself a finding about the gene and the disease.
gastric cancer (continued). "We first found that Tan IIA could induce ferroptosis in BGC-823 and NCI-H87 gastric cancer cells which was characterized by increased lipid peroxidation and Ptgs2, Chac1 expression." (PMID 32776119, 2020). "Consequently, these findings underscore the anti-neoplastic role of CHAC1 in gastric cancer." (PMID 38007439, 2023). "ALKBH5-mediated CHAC1 downregulation enhances GSH levels and strengthens antioxidant capacity, resulting in the increased proliferation of gastric cancer cells." (PMID 40227215, 2025). "In gastric cancer, ALKBH5-mediated m6A demethylation regulates the stability of target mRNAs, including CHAC1." (PMID 39534397, 2024). "To evaluate if ALKBH5 suppressed CHAC1 expression steadily in GC, we re-examined the total mRNA expression of CHAC1 after ALKBH5 knockdown in several gastric cancer cell lines." (PMID 38007439, 2023). "The results showed that inhibiting NEK2 expression increased HMOX1 mRNA and protein levels in gastric cancer cells, consistent with the results of RNA-seq, while CHAC1 levels did not change." (PMID 38503948, 2025). "To confirm our speculation, we used R scripts and website tools to conduct several bioinformatics analyses to investigate the clinicobiological function of CHAC1, NOX4 and HIF1A and the therapeutic potential of CHAC1, NOX4 and HIF1A in stomach cancer." (PMID 35023280, 2022).
melanoma (9 papers, 2019 to 2025). A malignant, usually aggressive tumor composed of atypical, neoplastic melanocytes. "Both ACSL4 and CHAC1 were positively correlated with miR-150-3p expression, and their low expression levels were associated with poor survival outcomes in melanoma patients in an independent cohort." (PMID 40860143, 2025). "This has been observed in cancers such as glioblastoma and melanoma, where ChaC1 overexpression has been linked to increased cell death and a reduction in tumor growth." (PMID 39534397, 2024). "In ferroptosis resistant melanoma cells, CHAC1 was shown to be upregulated by NRF2 independent from ER stress signaling alongside the Aldo-Keto Reductase Family 1 Member C1 (AKR1C1) capable of degrading lipid radicals." (PMID 41488051, 2025). "Despite the early upregulation of CHAC1, most melanoma cell lines appear to be resistant against ferroptosis." (PMID 41488051, 2025). "CHAC1 plays a significant role in mediating cell death in melanoma by acting downstream of GCDH (glutaryl-CoA dehydrogenase) inhibition." (PMID 39534397, 2024). "This positions CHAC1 as a key mediator in the ferroptotic pathway, linking oxidative stress responses to the execution of ferroptosis in melanoma cells." (PMID 39534397, 2024). "Furthermore, ACSL4 and CHAC1 expression levels were significantly lower in melanoma tissues than in matched normal samples." (PMID 40860143, 2025). "Consistent with our in vitro findings, genes associated with the ATF4 (e.g., ATF4, DDIT3, PPP1R15A and CHAC1), ATF6 (e.g., ATF6B, CALR, SEL1L, and EDEM1) and XBP1 (e.g., SSR3 and DELR1) pathways were significantly enriched in melanoma TILs compared with healthy blood T cells." (PMID 40335738, 2025). "However, we found that the UPR signaling pathway is not significantly induced upon ferroptosis induction in our panel of melanoma cell lines, thus indicating the existence of an ER stress-independent upregulation of CHAC1 under ferroptotic conditions." (PMID 31780644, 2019). "Interestingly we found that this non-apoptotic signaling pathway is efficiently induced in all cells of our panel of commercially available melanoma cell lines, as evidenced by the fast, consistent and sustained upregulation of the early marker CHAC1." (PMID 31780644, 2019). "Thus, CHAC1 could be a biomarker for a good response to checkpoint blockade in patients with melanoma." (PMID 37553341, 2023). "Similarly, the analysis of another cohort from Cancer-Immu algorithm suggested that CHAC1 expression was also elevated in melanoma patients who responded to CTLA-4 blockade therapy, and patients with higher CHAC1 expression had increased overall survival or progression-free survival." (PMID 37553341, 2023). "In contrast, miR-150-3p expression was positively correlated with YAP, ACSL4, CHAC1, and CD8+ T-cell infiltration and iron accumulation in melanoma tissues." (PMID 40860143, 2025). "A375 melanoma cells were subsequently pretreated with iEV-NC, iEV-150, or iEV-150 combined with sh-ACSL4 or sh-CHAC1 for 48 h before being cocultured with CD8+ T cells." (PMID 40860143, 2025). "The upregulation of CHAC1, along with other apoptotic genes like DDIT3, results in significant melanoma cell death." (PMID 39534397, 2024). "Consequently, CHAC1 acts as a critical mediator in the apoptosis pathway triggered by metabolic stress due to GCDH inhibition, highlighting its importance in the potential therapeutic targeting of melanoma." (PMID 39534397, 2024). "However, we observed that UPR is not required for ferroptosis in metastatic melanoma cells, despite a clear and early upregulation of CHAC1, that could be be abrogated by inhibiting NRF2, suggesting that CHAC1 is under control of both UPR and NRF2." (PMID 37021009, 2023).
glioma (8 papers, 2018 to 2024). A benign or malignant brain and spinal cord tumor that arises from glial cells (astrocytes, oligodendrocytes, ependymal cells). "Treatment of glioma cells with TMZ causes upregulation of CHAC1 expression, which is in turn correlated with enhanced apoptotic cell death via caspase 3/9 activation." (PMID 29316219, 2018). "CHAC1 is identified as a critical mediator in the cytotoxic effects of temozolomide (TMZ) on glioma cells, particularly through its interaction with the Notch3 pathway." (PMID 39534397, 2024). "In glioma cells, CHAC1 can bind to Notch3 protein and inhibit its activation under temozolomide induction, leading to inactivation of Notch3-mediated downstream signaling pathways." (PMID 35372041, 2022). "Another effect of TMZ‐induced upregulation of CHAC1 expression in glioma cells is the binding of CHAC1 to the NOTCH3 protein and consequent inhibition of NOTCH3 activation, resulting in attenuation of NOTCH3‐mediated pathways." (PMID 29316219, 2018). "Previous studies showed that CHAC1 protein expression is upregulated in glioma cells in response to treatment with Temozolomide (TMZ), the most common antiglioma chemotherapeutic agent, and that CHAC1 overexpression enhances glioma apoptotic death." (PMID 29316219, 2018). "In our study, Sev induced the expression of CHAC1 in glioma cells, and this effect could be attenuated by inhibiting ATF4 expression." (PMID 35372041, 2022). "It was observed that CHAC1 was the most upregulated gene after Temozolomide therapy of glioma." (PMID 31756991, 2019). "Moreover, TMZ‐induced upregulation of CHAC1 expression in glioma cells results in the binding of CHAC1 to the NOTCH3 protein and consequent inhibition of NOTCH3 activation, resulting in attenuation of NOTCH3‐mediated pathways." (PMID 29316219, 2018). "CHAC1, upregulated by TMZ via the JNK1/c-JUN signaling pathway, significantly enhances glioma cell death through mechanisms involving apoptosis, autophagy, ROS generation, increased intracellular calcium, and mitochondrial membrane potential loss." (PMID 39534397, 2024). "Increased CHAC1 levels, triggered by treatments like Temozolomide (TMZ), facilitate apoptotic processes and improve the effectiveness of anti-glioma therapies." (PMID 39534397, 2024). "Ex vivo slices from human gliomas showed both synergistic sensitivity to CMD and ferroptosis inducers as well as significant transcriptional upregulation of CHAC1 and SLC7a11 following CMD." (PMID 36864031, 2023). "Thus, CHAC1 acts as a suppressor of Notch3, enhancing the apoptotic and cytotoxic effects of TMZ on glioma cells." (PMID 39534397, 2024). "Additionally, CHAC1 inhibits the Notch3 signaling pathway by binding to Notch3 and preventing its activation, which further contributes to TMZ’s cytotoxic effects on glioma cells." (PMID 39534397, 2024).
Sepsis (8 papers, 2021 to 2025). Sepsis is defined as life-threatening organ dysfunction caused by a dysregulated host response to infection. "Studies have indicated that SESN2 can suppress ferroptosis of DCs in sepsis by downregulating the Atf4/Chop/Chac1 signaling pathway (Li J.-Y." (PMID 39944356, 2024). "Sestrin2 protects dendritic cells from sepsis-induced ferroptosis and may act as an antioxidant by downregulating the ATF4/CHOP/CHAC1 signaling pathway." (PMID 38023615, 2023). "In addition, in infectious diseases such as sepsis, lipopolysaccharide (LPS) induces ferroptosis in DCs, while Sestrin2 inhibits this process through the ATF4-C/EBP homologous protein (CHOP)-cation transport regulator homolog 1 (CHAC1) signaling pathway, thereby alleviating sepsis." (PMID 41154692, 2025).
Burkitt lymphoma (7 papers, 2021 to 2025). A rare form of malignant mature B-cell non-Hodgkin lymphoma. "In artesunate-induced ferroptosis in Burkitt’s lymphoma (BL) cells, CHAC1 is upregulated as part of the ATF4-CHOP-CHAC1 pathway activation." (PMID 39534397, 2024). "Artesunate (ART) enhances ferroptosis in Burkitt’s lymphoma cell lines by activating the ATF4/CHOP/CHAC1 pathway, an endoplasmic reticulum stress response." (PMID 38738174, 2024). "CHAC1 and CD44 have been suggested to interact with system Xc- and provide a proferroptotic effect in Burkitt’s lymphoma and an antiferroptosis effect in human gastrointestinal cancer, respectively." (PMID 34281531, 2021).
clear cell renal cell carcinoma (7 papers, 2021 to 2025). "CHAC1 is associated with ferroptosis and serves as a prognostic factor across various cancers, including renal clear cell carcinoma and stomach adenocarcinoma." (PMID 38300336, 2024). "Moreover, HHLA2 expression has been associated with the expression of ferroptosis-related gene ChaC Glutathione Specific Gamma-Glutamylcyclotransferase 1 (CHAC1), another prognostic factor in clear cell renal cell carcinoma." (PMID 38786018, 2024). "In addition, iron-related gene CHAC1 effectively indicates a poor prognosis of renal clear cell carcinoma." (PMID 37064151, 2023).
glioblastoma (7 papers, 2019 to 2025). The most malignant astrocytic tumor (WHO grade IV). "CHAC1 significantly functions in glioblastoma-initiating cells (BTICs) by promoting apoptosis and inhibiting NOTCH signaling." (PMID 39534397, 2024). "HiChIP data indicated increased chromatin interactions near MAP1LC3B and CHAC1 loci in ferroptotic glioblastoma cells." (PMID 37834393, 2023). "The findings suggest that targeting the CHAC1-Notch3 axis could provide new therapeutic strategies for treating glioblastoma (Chen P.-H." (PMID 39534397, 2024). "This interaction between CHAC1 and Notch3 offers potential therapeutic insights, suggesting that targeting CHAC1 could amplify TMZ’s efficacy against glioblastoma by mitigating Notch3 activity (Chen P.-H." (PMID 39534397, 2024). "Furthermore, ATF4 overexpression alone proved sufficient to induce CHAC1 expression in GBM cells, resulting in the generation of oxidized lipids and subsequent cell death in glioblastoma cells." (PMID 38291540, 2024). "In glioblastoma (GBM), HIF-2α induced by the prolyl hydroxylase (PHD) inhibitor roxadustat, upregulated ferroptosis regulatory genes such as ACSL4, PTGS2, and CHAC1, to enhance lipid peroxidation and erastin-induced ferroptosis, leading to the suppression of GBM cell growth in vitro and in vivo." (PMID 37048123, 2023).
diabetic kidney disease (6 papers, 2022 to 2025). Progressive kidney disorder caused by vascular damage to the glomerular capillaries, in patients with diabetes mellitus. "In diabetic kidney disease, the inhibition of CHAC1/nuclear factor kappa B can suppress inflammation in renal proximal tubular epithelial cells and repress the progression of diabetic kidney disease." (PMID 41245353, 2025). "The inhibition of CHAC1 is involved in suppressing the inflammatory response of renal proximal tubular epithelial cells and alleviating diabetic kidney disease." (PMID 41245353, 2025). "The regulation of CHAC1 by miR-26a-5p plays a crucial role in mitigating inflammatory responses in renal cells, particularly within the context of diabetic kidney disease (DKD)." (PMID 39534397, 2024). "For example, miR‐26a‐5p alleviated acute lung injury by targeting TLR4 to suppress inflammation and apoptosis, and it decreased inflammation in diabetic nephropathy by targeting CHAC1/NF‐κB pathway." (PMID 36756710, 2023). "Besides, miR-26a-5p also could attenuate the inflammation of diabetic kidney disease through targeting CHAC1." (PMID 35491874, 2022).
hepatocellular carcinoma (6 papers, 2020 to 2025). A malignant tumor that arises from hepatocytes. "For example, MIA3 has been shown to promote the degradation of GSH by binding to CHAC1, thus facilitating hepatocellular carcinoma progression." (PMID 39534397, 2024). "MIA3 further promotes the growth, metastasis, and invasion of hepatoma cells by binding to the CHAC1 protein and promoting GSH degradation." (PMID 37948019, 2024). "In this study, we systematically demonstrated that both genetic amplification (exogenous overexpression) and pharmacological induction (endogenous upregulation) of ChaC1 profoundly sensitized hepatocellular carcinoma (HCC) cells to auranofin (AUR) cytotoxicity." (PMID 41249117, 2025). "The regulation of CHAC1 and subsequent impact on tumor growth in hepatocellular carcinoma (HCC) remains debated." (PMID 39368995, 2024). "Therefore, the MIA3/CHAC1/GSH axis may be a new target for the diagnosis and treatment of hepatocellular carcinoma." (PMID 37948019, 2024).
uveal melanoma (6 papers, 2021 to 2024). A melanoma derived from melanocytes of the uveal tract. "Previous research studies suggested that CHAC1 was correlated with a high risk of metastasis and poor prognosis and exerted a harmful influence on clinical outcomes in uveal melanoma." (PMID 36120545, 2022). "The study concerning CHAC1 and uveal melanoma suggests that CHAC1 influences AKT activity indirectly by affecting this pathway." (PMID 39534397, 2024). "This regulatory relationship highlights CHAC1’s potential role in modulating oncogenic signaling pathways, making it a candidate for targeted therapy in diseases like uveal melanoma where PI3K/AKT signaling is dysregulated." (PMID 39534397, 2024). "CHAC1 is an effector of the endoplasmic reticulum stress pathway that has been shown to promote chemotherapy resistance in uveal melanoma cells." (PMID 35673577, 2022). "Furthermore, CHAC1 promotes cell proliferation and metastasis in uveal melanoma and is a potential therapeutic target." (PMID 39368995, 2024). "Inhibition of either HDAC4 or CHAC1 reduced the proliferation of uveal melanoma cells 102,103." (PMID 35673577, 2022). "Besides, we noticed the expression of CHAC1 is associated with various gene markers of immune cells as well as the checkpoint genes in LUAD, LUSC, PRAD, BRAC and especially, in uveal melanoma (UVM)." (PMID 33728749, 2021).
cystic fibrosis (5 papers, 2018 to 2025). Autosomal recessive disorder caused by pathogenic variants in the CFTR gene (cystic fibrosis transmembrane conductance regulator), which encodes a chloride and bicarbonate channel expressed in epithelial cells, and follow the diagnosis criteria. "In H. pylori infection, CHAC1 contributes to gastric cell oxidative stress and mutations that could potentially lead to cancer, while in cystic fibrosis, reduced CHAC1 levels contribute to chronic inflammation by impairing the body’s ability to regulate oxidative stress." (PMID 39534397, 2024). "Whereas non-cystic fibrosis cells upregulate CHAC1 following infection with various pathogens (including Pseudomonas aeruginosa, human coronavirus, cytomegalovirus, tick-borne flaviviruses, Zika virus, and Mycoplasma hominis), cystic fibrosis cells show an impaired response." (PMID 41488051, 2025).
lung carcinoma (5 papers, 2024 to 2025). "The researchers employed both loss-of-function and gain-of-function approaches to modulate CHAC1 expression in lung cancer cells, utilizing RNA interference for gene knockdown and plasmid transfection for overexpression." (PMID 40142049, 2025). "Treatment with hederagenin in lung cancer cells, leads to a strong upregulation of the CHAC1 gene even though basal CHAC1 expression is significantly lower than in normal tissues." (PMID 41488051, 2025). "Functional rescue experiments and in vivo studies further confirmed that downregulation of CHAC1 reversed the HG-induced promotion of lung cancer cell death." (PMID 40142049, 2025). "For instance, CHAC1 has been found to be upregulated in lung cancer." (PMID 39595659, 2024). "However, current studies have mainly focused on bioinformatic analysis and not in-depth mechanistic studies, and the role of CHAC1 in lung cancer progression remains unclear." (PMID 39368995, 2024). "In the lung cancer group, PRKG2 exhibited significant positive correlation with NFE2L2, SLC40A1, TFRC, and significant negative correlation with CHAC1 and HSPB1." (PMID 39744538, 2024).
prostate carcinoma (5 papers, 2023 to 2025). A carcinoma that arises from epithelial cells of the prostate gland. "In a study on prostate cancer, cancer-associated fibroblasts (CAFs) were found to secrete exosomal miR-432-5p, which plays a crucial role in promoting chemoresistance in prostate cancer cells by targeting CHAC1." (PMID 39534397, 2024). "Overexpression of CHAC1 in prostate cancer cell lines DU145 and 22RV1 significantly reduces cell viability and GSH levels, while its knockdown increases viability in DU145 cells." (PMID 39534397, 2024). "Overexpression of CHAC1 in prostate cancer cells increased intracellular lipid peroxidation and decreased levels of GPX4, promoting ferroptosis and enhancing sensitivity to docetaxel." (PMID 39534397, 2024). "CHAC1, a proapoptotic protein involved in ER stress, shows decreased expression in prostate cancer cells compared to normal prostate epithelial cells." (PMID 39534397, 2024). "ChaC glutathione specific γ-glutamylcyclotransferase 1 (CHAC1) can decrease the content of intracellular GSH to prompt ferroptosis in prostate cancer cell with increasing the sensitivity of prostate cancer cells to docetaxel." (PMID 36056183, 2023). "For prostate cancer, CHAC1 potentiates docetaxel cytotoxicity via coordinated induction of endoplasmic reticulum stress and ferroptosis, yet its suppression by cancer-associated fibroblast-derived exosomal miR-432-5p establishes therapy-reinforced chemoresistance." (PMID 40860820, 2025). "For prostate cancer, CHAC1 critically regulates therapeutic responsiveness." (PMID 40860820, 2025). "Additionally, stage-specific regulatory networks in ccRCC and CHAC1-androgen receptor crosstalk in prostate cancer warrant deeper mechanistic dissection." (PMID 40860820, 2025). "Additionally, CHAC1 enhances the sensitivity of prostate cancer cells to the chemotherapy drug docetaxel (DTX)." (PMID 39534397, 2024). "CHAC1 inhibits cell viability and increases the sensitivity of prostate cancer cells to DTX by inducing ER stress and iron death in prostate cancer." (PMID 37948019, 2024).